LYVE1 (lymphatic vessel endothelial hyaluronan receptor 1)
Diseases named in the same sentence as LYVE1 in open-access papers (continued):
Sharing a sentence is not in itself a finding about the gene and the disease.
tumor (continued). "Furthermore, by analyzing immunohistochemical staining with anti-LYVE-1 antibodies of tumor tissues, they found out that miR-128 could suppress lymphangiogenesis of tumor xenografts in vivo, suggesting the therapeutic significance of miR-128 in NSCLC." (PMID 31616631, 2019). "Our methodology reveals β4 integrin throughout the tumor; however, within lymphatic vessels, there is differential distribution of β4 integrin with relative increases in β4 accumulation observed in lymphovascular areas proximal to Lyve1+ lymphatic endothelial cells (LECs) (white arrow)." (PMID 31091437, 2019). "Very few Lyve1+ lymph vessels could be observed within the central parts of the tumors, however, in the peripheral parts, lymph vessels that contained inflammatory cells and tumor cells were sometimes seen." (PMID 28472073, 2017). "Furthermore, LYVE-1 is the specific marker of lymphatic vessels in tumor lymphangiogenesis." (PMID 27166194, 2016). "Therefore, downregulation of those 3 molecules (Lyve1, Prom1, Lcn2) could be responsible for lower migration capabilities of tumor (metastatic) cells in AMEC-KO mice." (PMID 27640364, 2016). "However, the mechanism by which tumor cell surface HA acts on LYVE-1 to affect its adhesion and transfer in tumor lymphatic metastasis remains unclear." (PMID 23717428, 2013). "However, whether low HA content in tumor cells produces an interaction with LYVE-1 through other factors to influence tumor cell adhesion is still unclear." (PMID 23717428, 2013). "Furthermore, we observed for the first time that the cell surface HA content of high transfer tumor cells was rich, and we visualized the cross-linking of HA cable structures, which may activate LYVE-1 on lymphatic endothelial cells, promoting tumor adhesion." (PMID 23717428, 2013). "However, it was unclear whether HA on the surface of tumor cells develop into cable structures and play a role in activating LYVE-1." (PMID 23717428, 2013). "LYVE-1 may promote tumor lymph node metastasis and lymphatic invasion." (PMID 20374665, 2010). "Immunostaining for lymphatic markers such as LYVE-1 and podoplanin in routine histological work-up of tumour samples might be warranted if future studies reveal a correlation between tumour-induced lymphangiogenesis and prognosis of the tumour in terms of metastasis and recurrence rate." (PMID 19628489, 2009). "Subsequently, the expression levels of LYVE-1 in murine tumor tissues by IHC were strongly correlated with the circPDLIM5 levels, but the expression of PROX1 was low in tumor tissues." (PMID 40611320, 2025). "Tumor-recruited M-LECPs retained this profile in vivo as shown by expression of prominent fusogenic markers SIRP-a, CD36, and DAP12 in 60–90% of LYVE-1+ cells in mouse and human BC." (PMID 40507286, 2025). "Bulk RNAseq data generated in this study is available GSE248272 (bulk tumor) and GSE287874 (isolated LYVE-1+ TAMs)." (PMID 40768602, 2025). "To gain further insight into tumor infiltration into the vessel-like structures, we performed IHC staining using CD31, a blood vessel endothelial cell marker, and LYVE1, a lymphatic endothelial cell marker." (PMID 41028519, 2025). "IL-17A promotes OPN secretion by tumor cells, activating LYVE-1/JNK/c-Jun signaling to expand immunosuppressive LYVE-1+ macrophages." (PMID 40092996, 2025). "To confirm database results, we evaluated the expression of LYVE‐1 in clinical paraffin embedded samples, revealing that patients with higher SOAT1 expression exhibited higher expression of LYVE‐1 in tumor tissues." (PMID 40135589, 2025). "Soluble LYVE-1 (sLYVE-1) is generated locally through MT1-MMP activity and then released into the tumor stroma." (PMID 40507943, 2025). "Differential expression analysis between macrophages from the tumor and normal tissue identified genes that are enriched specifically within TAMs (TREM2, GPR84 and SPP1) and tissue-resident macrophages (LYVE1), which is consistent with previous observation." (PMID 38349405, 2024).
tumor (continued). "Fc-EndoP125A treatment did not decrease the total amount of tumor vasculature, but mice exhibited smaller tumor vessels and markedly decreased CD34+ and LyVE-1+ tumor vessel density compared to PBS- and Rituximab-treated mice." (PMID 39594584, 2024). "The tumor markers of KHE, such as platelet endothelial cell adhesion molecule-1 (CD31) and LYVE-1, were evaluated." (PMID 38486263, 2024). "To measure tumor vascularity, we performed IHC using anti-murine CD34 to stain blood vessels and anti-murine LyVE-1 to stain lymphatic vessels." (PMID 39594584, 2024). "ITIHs, LYVE-1, RHAMM, HAPLN1, and PHBP levels are elevated in certain tumour types, while decreased expression of these HAIMs has been evident in other malignancies." (PMID 38791985, 2024). "Consistently, subsets expressing T-cell and erythroid markers lost a lymphatic marker Lyve-1 and were physically segregated from M-LECP by migrating to independent tumor locales." (PMID 38640116, 2024). "More than 90% of tumor-recruited GFP+ cells co-expressed myeloid CD11b and lymphatic Lyve-1 markers." (PMID 38640116, 2024). "HA is a ligand for various cell surface receptors (CD44, LYVE-1, RHAMM, and HARE) that are overexpressed in tumor cells and nanogels preferentially accumulate in tumor tissues due to the enhanced permeability and retention (EPR) effect." (PMID 39339063, 2024). "Dual immunofluorescence showed that PDGFR-β was expressed in both tumor cells (CK19+) and LECs (labeled by PDPN, LYVE-1 or PROX-1)." (PMID 37307823, 2024). "Immunofluorescent staining of α-SMA, LYVE-1 and DAPI were examined in primary tumour samples obtained from 57 CSCC patients." (PMID 37415190, 2023). "TAMs produce pro-lymphangiogenic factors such as lymphatic vessel endothelial hyaluronan receptor 1 (LYVE-1) and a glycoprotein YKL-40 to support tumor lymph-angiogenesis." (PMID 38258072, 2023). "Briefly, knock-down of MEF2C-AS1 promoted aggressive tumor behaviors by reducing the protein levels of FAT3, NTN1, and LYVE1 which were related to proliferation and invasion in GC cell lines." (PMID 36064442, 2022). "To evaluate the extent of infiltration of CCA cells to LNs and LEC infiltration in CCA TME we stained tumor and liver LN section from orthotopic CCA mice with CK19/Podoplanin and CK19/LYVE1 respectively." (PMID 34831316, 2021). "However, LYVE1 might also play anti-tumor role in some cancers." (PMID 34249481, 2021). "HA receptors (especially CD44, hyaluronan-mediated motility receptor RHAMM, lymphatic vessel endothelial hyaluronic acid receptor 1 LYVE1) are activated in cancer cells to promote cell infiltration and tumor malignancy." (PMID 33613290, 2021). "Afatinib inhibited LYVE-1, VEGFR2, VEGFR3, VEGFC, VEGF, and CCR7 expression in a dose-dependent manner in HCC827 xenograft tumour tissues, and these results demonstrated the anti-lymphangiogenic action of Afatinib." (PMID 31892990, 2020). "Using total protein from HCC827 xenograft tumour tissues, we found that Afatinib inhibited the phosphorylation of JAK1,2, STAT3, and FAK, the protein expression of LYVE-1, VEGFR2, VEGFR3, VEGFC, VEGFA, and CCR7." (PMID 31892990, 2020). "Using the NSCLC tumour model, we found that Afatinib suppressed the expression of LYVE-1, VEGFR2, 3, VEGFC, and VEGF in tumour tissues, indicating reduced lymphatic formation and possible VEGFC/VEGFR3 pathway involvement in the process." (PMID 31892990, 2020). "Specifically, we stained the tumor tissue for the presence of endothelial cell marker CD31 of both human and mouse origin, and mouse Lyve-1, a protein found on lymphatic endothelial cells." (PMID 32958605, 2020). "Some of the empty space within the tumor appears to be microvessels as determined by CD31 and LYVE1 staining, however there is noticeably a lack of blood cells within them." (PMID 33028899, 2020). "In this prognostic signatures, high expression of RGS16, LYVE1, hnRNPC, ANP32A, and AIMP1 focus in promoting cell proliferation and tumor progression." (PMID 33329703, 2020).
tumor (continued). "Accordingly, mice with downregulated ANRIL had lower tumor growth rates and decreased levels of VEGF-C, VEGFR-3, and LYVE-1." (PMID 33172072, 2020). "Tumour lymphangiogenesis was analysed using immunofluorescent staining with VEGFR‐3 and lymphatic vessel endothelial hyaluronan receptor 1 (LYVE‐1) antibodies." (PMID 30648805, 2019). "Expression of miR526b and miR655 in human tumour tissue was significantly correlated with lymphangiogenesis markers VEGFC, VEGFD, and LYVE-1." (PMID 31277414, 2019). "The tumor formed by MGC803/ miR-509-3-5P/sponge developed more level of microlymphatic vessel density (MLD), marked by Lyve-1 positive microvessel, as compared with mock and control group." (PMID 28432273, 2017). "This molecular OCT method enables in vivo imaging of the expression profiles of lymphatic vessel endothelial hyaluronan receptor 1 (LYVE-1), a biomarker that plays crucial roles in inflammation and tumor metastasis." (PMID 28439123, 2017). "The tumor angiogenesis and lymphangiogenesis were assessed by immunohistochemical staining with anti-CD31 and anti-LYVE1 antibodies." (PMID 28423625, 2017). "Real-time quantitative PCR (RTQ–PCR) was used to check the expression levels of LYVE–1, VEGFR–3, Podoplanin, and Prox–1 in tumor and para-cancerous tissues." (PMID 29162097, 2017). "Second, inflammation and tumor-mobilized BMDM often express lymphatic-specific markers such as VEGFR-3, LYVE-1, and podoplanin (PDPN)." (PMID 28598999, 2017). "The positive expression rates of LYVE–1, VEGFR–3, Podoplanin, and Prox–1 in tumor tissues were 100, 93.6, 100, and 91.4%, but 100, 100, 100, and 87.2% in para-cancerous tissues." (PMID 29162097, 2017). "Accordingly, histologic analysis showed that NCoR depletion was sufficient for promoting tumor lymphangiogenesis, resulting in increased LYVE-1 gene expression and in increased density of LYVE-1–positive lymphatic vessels." (PMID 27806339, 2016). "Immunohistochemistry (IHC) staining showed that most tumor cells expressed KS-specific viral/cellular marker molecules, such as LANA, CD31 and LYVE-1." (PMID 26675551, 2016). "Tumor capillaries were identified using immunohistochemical CD31 staining for blood vessels and hyaluronan receptor‐1 (LYVE‐1) staining for lymphatic vessels." (PMID 27650585, 2016). "To answer this question, we analyzed 62 lymphatic vessels in healthy skin as control and 80 intratumoral lymphatic vessels in primary Ret tumor cryosections stained for VWF and Lyve-1." (PMID 27602496, 2016). "Tumors derived from lithium-treated mice showed a very low density of lymphatic vessels stained with LYVE-1/CD31 in the peri-tumoral (margin of tumor) and intratumoral (central region of tumor) areas." (PMID 26857144, 2016). "Treatment with propranolol during MDA-MB-231 tumour development blocked chronic stress from increasing tumour LYVE-1+ LVD and reduced metastasis to lymph nodes, suggesting that reduced LVD had functional effects on tumour cell dissemination." (PMID 26925549, 2016). "To verify this finding at a microscopic level we stained tumor sections for CD31 and for lymphatic endothelium specific antigen-1 (LYVE-1) to compare the density of blood vessels (CD31+, LYVE-1−) in both types of tumors." (PMID 23251384, 2012). "Labeling of LYVE-1 (lymphatic marker) and CD31 (blood vessel marker) in tissue sections clearly revealed a lymphatic origin of these tumor cell-containing vessel-like structures." (PMID 23049897, 2012). "In addition, to determine whether or not the tumor cell nests circumscribed with LYVE-1-positive lymphatic endothelial cells are in dilated lymphatic vessels, we performed Masson staining to visualize tumor-associated fibrous stroma." (PMID 21034514, 2010). "Recently, several markers for lymphatic endothelium have been discovered, including transmembrane protein lymphatic vessel endothelial hyaluronan receptor-1 (LYVE-1), and these provide powerful tools for studying tumor lymphangiogenesis." (PMID 19232130, 2009).
tumor (continued). "And it has been demonstrated that LYVE1+ TAMs represent a progressive subcluster that contributes to tumor expansion even in the absence of the omentum." (PMID 41341850, 2025). "This study has unveiled a novel finding that tumor cell-derived LMW-HA-induced S1PR1 endocytosis could trigger lymphangiogenesis, in which LYVE-1-mediated enhancement of Src phosphorylation may be responsible for the underlying mechanism." (PMID 39991586, 2025). "However, X‐irradiated tumours, though smaller, showed higher expression of lymphatic (Lyve1) and vascular markers (CD31), indicating a more aggressive molecular profile than P‐irradiated tumours." (PMID 40400121, 2025). "We also used two methods to identify tumor-recruited M-LECP based on either GFP expression in in vitro differentiated progenitors derived from BM of GFP+ mice or co-expression of Lyve-1 and CD11b markers in the absence of GFP." (PMID 38640116, 2024). "While LYVE‐1+ macrophages have been widely reported to have pro‐tumor properties and make a tempting target for clinical inhibition, the expression of LYVE‐1 is not restricted to macrophages." (PMID 38426622, 2024). "Interestingly, we observed that the tumour model with the highest level of PHPMA accumulation, that is, CT26, had almost double the number of LYVE-1+ lymphatic vessels as A431 and MLS." (PMID 38589466, 2024). "Most if not all tumours grow in close proximity to host lymphatics or generate new peritumoral or even intratumoral lymphatics, both of which have LYVE-1 lined endothelial junctions." (PMID 37606814, 2024). "In the human PDAC patient tumor transcriptome (TCGA), we identify strong and significant correlations between tumoral GHR expression and known lymphangiogenic (LYVE1, FLT4, VEGFC, and PDPN) and angiogenic (PDGFRa, FGFR1, TGFB3, TGFB1, TGFBR2, HIF1a, IL6, and IL1B) markers." (PMID 39000545, 2024). "Thus, the depletion of LYVE-1+ macrophages results in increased CD8+ T-cell infiltration, which correlates with the reduction in primary tumor growth." (PMID 38717149, 2024). "For example, macrophages expressing LYVE-1 and other LEC-related markers, such as podoplanin (PDPN), have been shown to localize to lymphatic regions and contribute to lymphangiogenesis in various tumor models." (PMID 38717149, 2024). "Notably, circUBE2G1 overexpression significantly increased the density of LYVE-1-positive microlymphatic vessels (MLD) in the intratumoral and peritumoral areas of footpad primary tumor tissues, confirming that circUBE2G1 promotes lymphangiogenesis in LUAD." (PMID 39664183, 2024). "Indeed, GFP-DTR+ Treg cells were found in markedly closer proximity to Lyve-1+ LECs, GP38+ fibroblasts and F4/80+ macrophages within and near tumor nodules than in areas further away from tumor nodules in the same tumor-bearing lung." (PMID 37127830, 2023). "In contrast, ANGPTL2 blockade suppressed tumor growth and the levels of ANGPTL2, LYVE-1 and VEGF-A." (PMID 36917086, 2023). "As of yet, the involvement of LYVE-1/Lyve-1 in tumor cell adhesion to LSECs and hepatic metastasis has not been studied." (PMID 36496412, 2022). "Metronomic DOX treatment also resulted in a significant decrease in lymphatic endothelial VEGFR-3 expression and LYVE-1+ tumor lymphatic vessel density in the WT but not Redd1−/− mice." (PMID 34697389, 2021). "In this study, we present a potential novel mechanism of lymphatic metastasis in OSCC—lymphatic mimicry (LM), a process whereby tumour cells form cytokeratin+/LYVE-1+, but podoplanin-negative, mosaic endothelial-like vessels." (PMID 33674563, 2021). "We designed an antibody cocktail of lineage markers (CD24, CD31, CD45.2, CD49f, EpCAM, TER-119 and LYVE-1) to exclude non-fibroblast cells from the single cell suspension of tumours analysed by flow cytometry (FCM)." (PMID 34016130, 2021).
tumor (continued). "Together, our findings uncovered, to our knowledge, a previously unknown expression and function of LYVE-1 in OSCC, whereby tumour cells could induce LM formation and promote lymphatic metastasis." (PMID 33674563, 2021). "The exact biological effect of the Lyve-1/hyaluronic acid interaction in myeloid cells has not yet been clarified, but, in various tumor types, Lyve-1+ macrophages have been primarily found in the marginal zone and not the central hypoxic region." (PMID 33266104, 2020). "The tumor tissues in the groups E10 and G11 were paraffin-embedded and the sections were immunohistochemically stained with antibodies for EGFL6, FGF-2, PDGFβ, VEGFA, CD31, and LYVE1." (PMID 32983976, 2020). "To assess the effect of treatments on tumor neoangiogenesis and lymphangiogenesis, we analyzed the expression of CD31 marking blood vessels and LYVE-1 marking lymphoid vessels by immunofluorescence in cryostat sections cut in OCT, which allows optimal retention of the structural micro-architecture." (PMID 31936526, 2020). "Co-immunofluorescence using antibodies directed against LYVE1 and cytokeratin 7, an antigen expressed in ES2 cells, revealed that the‬‏ metastasizing cells originated from the transplanted ES2 tumor cells (arrow)." (PMID 32132179, 2020). "In the extraocular tumor component, all tumors of that study showed subconjunctival peritumoral vessels that were LYVE-1 (+) and podoplanin (+), but notably no intratumoral recruitment was observed." (PMID 30781402, 2019). "Since HA accumulates in the tumor interstitial fluid, the binding of LMW-HA to LYVE-1 on endothelial cells could thus promote tumor lymphangiogenesis and thereby the formation of metastases." (PMID 29262593, 2017). "In the tumor tissues, OL reduced HFD-induced expression of angiogenesis (CD31, VE-cadherin, VEGF-A, and VEGFR2), lymphangiogenesis (LYVE-1, VEGF-C, VEGF-D, and VEGFR3), and hypoxia (HIF-1α and GLUT-1) markers as well as HFD-induced increases in lipid vacuoles and M2 macrophages (MΦs)." (PMID 28410190, 2017). "Immunofluorescent double staining was carried out on tumor tissues with VEGFR3 and LYVE-1, which are markers for LECs, and the results demonstrated that the mean micro-LVD of the tumors decreased from 13.4 ± 2.3 to 4.2 ± 1.3 as a result of treatment with fucoidan (120 mg/kg)." (PMID 27203545, 2016). "Similar to the network formed in the non-tumor subcutaneous matrigel model, the tumor-associated macrophage network also stained with endothelial markers CD31 and lymphatic marker LYVE1 (SI." (PMID 27834402, 2016). "The immunohistochemical analysis and TUNEL apoptosis assays and LYVE-1 staining were performed to directly evaluate whether YL529 could inhibit the tumor lymphangiogenesis and induce tumor cell apoptosis in vivo." (PMID 26187637, 2015). "LYVE-1 stained liver sinusoidal endothelial cells and was not able to identify lymphatic vessels in the tumor." (PMID 24963215, 2014). "COS-7 cells transfected with LYVE-1 (COS-7LYVE-1(+)) and SVEC4-10 cells (a lymph endothelial cell-like cell line) were used as the models to study the adhesion effect between LYVE-1 and tumor cells expressing high or low levels of HA." (PMID 23717428, 2013). "HA cables may have the same capacity to activate LYVE-1 as their capacity to activate CD44 in vivo, and our results as well as the findings of previous reports showed that some tumor surfaces contain high levels of HA." (PMID 23717428, 2013). "The presence or absence of lymphatics in the primary tumours was assessed by immunohistochemical expression of LYVE-1 and podoplanin." (PMID 22612847, 2011). "With respect to CCL21: Lymph nodes from wildtype mice that were not challenged with tumor were characterized by minimal CCL21 immunoreactivity distributed in the matrix surrounding LYVE-1-positive lymphatic vessels." (PMID 21172016, 2010).